INS (insulin)
Diseases named in the same sentence as INS in open-access papers (continued):
Sharing a sentence is not in itself a finding about the gene and the disease.
type 1 diabetes (continued). "Numerous clinical studies have shown the beneficial therapeutic effects of DPP-4 inhibitors in type 1 diabetes, where they decreased prandial insulin dose and total daily dose (TDD) of insulin, inhibited glucagon secretion and reduced blood glucose levels." (PMID 39271520, 2024). "In human pancreatic islets with type 1 diabetes, fasting conditions decrease PKA and mTOR activity, leading to the expression of specific genes and subsequent insulin production." (PMID 38321992, 2024). "Type 1 diabetes mellitus (T1DM) is an autoimmune condition that begins by targeting the beta cells of the pancreas, eventually destroying them and depleting endogenous insulin secretion in the body." (PMID 38800168, 2024). "It has been confirmed that MSC transplantation into STZ-induced type 1 diabetic mouse and NOD models can enhance islet regeneration, lower blood sugar, and increase blood insulin levels." (PMID 38533089, 2024). "Over the past 25 years, the knowledge about type 1 diabetes has rapidly expanded leading to progress in clinical disease management, including continuous glucose monitoring (CGM), insulin pumps and hybrid closed-loop insulin systems (HCLs)." (PMID 38780786, 2024). "However, disease progression is impossible to predict precisely and having IAb+ status does not mean imminent type 1 diabetes onset; stage 3 type 1 diabetes, with associated insulin administration and glycaemic monitoring, could be months or even years away." (PMID 38910151, 2024). "In hybrid automatic insulin delivery (HAID) systems, meal disturbance is compensated by feedforward control, which requires the announcement of the meal by the patient with type 1 diabetes (DM1) to achieve the desired glycemic control performance." (PMID 38956183, 2024). "Icodec insulin has been evaluated in various phase 3 studies in patients with T2DM and type 1 diabetes, included in the ONWARDS program." (PMID 38559691, 2024). "Type 1 diabetes mellitus (T1D) arises from the autoimmune destruction of pancreatic beta cells, culminating in the complete depletion of insulin production, but the exact mechanism behind T1D remains unclear." (PMID 39337936, 2024). "Additionally, persons experiencing DD may report challenges keeping up with type 1 diabetes self-care responsibilities and the use of less adaptive coping strategies (e.g., guessing an insulin dose to avoid checking glucose levels or skipping an insulin bolus altogether)." (PMID 39457134, 2024). "The antigen-presenting cell function of insulin-reactive B cells promotes type 1 diabetes (T1D) in non-obese diabetic (NOD) mice by stimulating pathogenic T cells leading to destruction of insulin-producing β-cells of pancreatic islets." (PMID 38515750, 2024). "Moreover, the effect of the herein described DNA-based dietary intervention could be explored in other clinical conditions where glucose management is impaired, for instance in individuals with T2DM (insulin independent or dependent), or individuals with Type 1 Diabetes." (PMID 38443427, 2024). "Endogenous insulin supplementation is essential for individuals with type 1 diabetes (T1D)." (PMID 39279997, 2024). "In the pathogenesis of type 1 diabetes (T1DM), insulin production is inhibited due to the destruction of pancreatic β cells during the autoimmune process." (PMID 39408157, 2024). "The online survey was compiled by 182 individuals with type 1 diabetes: 45.6% continuous subcutaneous insulin infusion (CSII) users and 54.4% multiple daily insulin injection users." (PMID 36801976, 2023). "In the case of the pancreatic islets seen in type 1 diabetes, the periods of fasting decrease the activity of PKA and mTOR and induce Sox2 and Ngn3 expression and insulin production." (PMID 36771207, 2023). "Streptozotocin-treated type 1 diabetes model mice showed induced expression of the CAR target gene, Cyp2b10, following an increase in blood glucose levels, and insulin treatment clearly attenuated these inductions." (PMID 36835365, 2023).
type 1 diabetes (continued). "In human studies, IGFBP2 has been reported to correlate inversely with insulin levels, and in the cross-sectional serum proteomics study by Zhi and co-workers, elevated IGFBP2 was observed and validated in individuals with type 1 diabetes." (PMID 37537394, 2023). "Type 1 diabetes (T1DM) is the most common chronic disease in young adults and children, which is treated with insulin, usually given as basal and boluses." (PMID 37046861, 2023). "The aim of the study was to adapt the German version of the insulin pump therapy (IPA) questionnaire to Italian (IT-IPA) and to evaluate its psychometric properties in adults with type 1 diabetes." (PMID 36801976, 2023). "Unlike type 1 diabetes, caused by immune-mediated loss of pancreatic β-cells, or type 2, caused by insulin resistance in glucose consuming tissues, dysregulation of glucose homeostasis in mtDB appears to occur when mitochondrial dysfunction leads to an impairment of β-cell insulin secretion." (PMID 37586651, 2023). "For people living with type 1 diabetes (PLWT1D), daily insulin administration is necessary to manage blood glucose (BG) levels." (PMID 37291520, 2023). "Despite previous reports that the cathepsin family promotes apoptosis, it has only been reported to protect insulin-secreting and immune β-cells against cytokine-induced apoptosis by perturbing the JNK pathway in type-1 diabetes." (PMID 36982347, 2023). "In the HypoCOMPaSS RCT, participants with type 1 diabetes and IAH were allocated to insulin pump therapy (continuous subcutaneous insulin infusion, CSII) or multiple daily insulin injections (MDI) for insulin delivery." (PMID 36538062, 2023). "Here we attempt to resolve that dilemma in part by reporting the first sufficiently powered study of adult-onset type 1 diabetes, including LADA, using dipeptidyl peptidase 4 (DPP-4) inhibitor and vitamin D as an adjunct to insulin and metformin." (PMID 37076476, 2023). "Moreover, exposure of the ovary and adrenals to the exogenous hyperinsulinism that results from the supraphysiological subcutanous insulin doses needed to control gluconeogenesis at the liver, may increase the prevalence of this androgen excess syndrome among women with type 1 diabetes." (PMID 36793089, 2023). "While for type 1 diabetes (T1DM), insulin is the only drug of choice in addition to lifestyle modification." (PMID 37743416, 2023). "Among the 49 people with type 1 diabetes and GI, 73.5% used continuous glucose monitoring (CGM) or flash glucose monitoring (FGM), and 61.4% had an insulin pump." (PMID 38317711, 2023). "The other two patients were insulin treated, and the prior probability for MODY is much lower in this group, since type 1 diabetes is the most common diagnosis in such patients." (PMID 37033247, 2023). "Significantly in type 1 diabetes, DKA can develop within hours if you stop insulin injections or an insulin pump malfunctions." (PMID 37363479, 2023). "Our previous study demonstrated that abnormal blood glucose, insulin, and lipid levels were present in STZ-induced type 1 diabetes mice, and HNCP ameliorated the abnormality of these indicators." (PMID 37888453, 2023). "Since the discovering of insulin by Frederick G Banting, Charles H Best and JJR Macleod, many efforts have been conducted sequentially to regulate of blood glucose level (BGL) for type-1 diabetic patients (T1DPs)." (PMID 37667042, 2023). "Type-1 diabetes (T1DM) is an autoimmune disease due to selective β-cell destruction and insulin secretion defects." (PMID 36771307, 2023). "This work may also be useful for people with type-1 diabetes or other people with glucose-metabolism disorders who visit high altitude due to the lower insulin levels observed among participants upon arrival, higher insulin levels within a few days of arrival, which then decrease." (PMID 37981980, 2023). "CLC insulin delivery exhibits significantly better day and night efficacy and safety than SAP therapy in adolescents with type 1 diabetes." (PMID 37574494, 2023).
type 1 diabetes (continued). "Type 1 diabetes (T1D) is a condition that results from the destruction of a type of cell in the pancreas that produces the hormone insulin, leading to lifelong dependence on insulin injections." (PMID 37794169, 2023). "Type 1 diabetes mellitus (T1D) is a chronic auto-immune disease that impairs insulin production." (PMID 37791586, 2023). "Type 1 diabetes mellitus (T1DM) results from the autoimmune destruction of β-cells in the pancreas and requires daily exogenous insulin replacement therapy." (PMID 37297929, 2023). "Another dietary intervention trial is The Finnish Dietary Intervention Trial for the Prevention of Type 1 Diabetes (FINDIA), which assessed the impact of complete avoidance of bovine insulin in infants in Finland." (PMID 37297566, 2023). "Young ladies with type 1 diabetes frequently experience recurrent DKA, which is primarily brought on by failing to administer insulin therapy." (PMID 37363479, 2023). "Also, the development of new smartphone apps designed for people with type 1 diabetes can improve time in range and diminish time below range by suggesting the appropriate amount of carbs before or after exercise and by helping the patient to adjust his/her insulin regimen." (PMID 37629520, 2023). "Adolescents and young adults with type 1 diabetes and coexisting CD had a trend towards higher TDD of insulin, less BP measurements in the hypertensive range and elevated BMI." (PMID 37338603, 2023). "Recently, another child with type 1 diabetes and SDS was also reported to be effectively treated with insulin pump therapy (CSII)." (PMID 37580732, 2023). "INS/DFAN also exhibited high encapsulation efficiency, excellent stability, and enhanced insulin delivery, whereas in vivo experiments on type 1 diabetic rats demonstrated improved hypoglycaemic effects and improved insulin bioavailability over INS/FAN." (PMID 36826291, 2023). "The management of type 1 diabetes (T1DM) involves frequent blood glucose monitoring and continuous adjustment of insulin delivery in order to maintain blood glucose within a narrow range as close as possible to normoglycemia." (PMID 37855262, 2023). "Type 1 diabetes mellitus (T1DM) is a chronic autoimmune disease characterized by the destruction of pancreatic β-cells, responsible for insulin production." (PMID 37836392, 2023). "In people with type 1 diabetes (T1DM), as levels of insulin and C-peptide fall, Na+/K+-ATPase and NO are disrupted, resulting in neuronal dysfunction, axonal swelling, oxidative stress and apoptosis." (PMID 35888162, 2022). "Thus, unlike women with type 1 diabetes and eating disorders who use insulin omission as a calorie-purging technique, our participants did not omit or manipulate medication for weight-loss purposes, though only three participants in our study used insulin." (PMID 36221145, 2022). "In an in vivo murine model of Type 1 Diabetes (T1D), cathelicidin-related antimicrobial peptide (CRAMP) is expressed in insulin producing β-cell islets." (PMID 35634307, 2022). "Therefore, therapies based on multiple daily injections (MDI), the combination of slow-acting insulin for basal coverage and rapid-acting insulin at mealtimes to control postprandial blood glucose levels, are still the most widespread treatments for people suffering from type 1 diabetes." (PMID 35214566, 2022). "Since β-cell secretory function is severely impaired in STZ-induced models of type 1 diabetes, the effect of CX3CL1 on insulin secretion would be difficult to identify in the present study." (PMID 35370759, 2022). "Our data show that the HARPdoc trial successfully recruited a cohort of people with type 1 diabetes, IAH and recurrent SH that has persisted despite optimised conventional self-management of their insulin regimens." (PMID 35325258, 2022). "Previous work showed that CM (plus honey) consumption decreased circulating glucose, increased insulin concentrations, and increased IGF-1 concentrations in type 1 diabetic rats." (PMID 35804599, 2022).
type 1 diabetes (continued). "Two hundred seventy-five subjects (147 males and 128 females) with insulin-dependent diabetes (treated with Multiple Daily Injections, MDI, or Continuous Subcutaneous Insulin Infusion, CSII) diagnosed in childhood were included in the study." (PMID 35769090, 2022). "This episode was characterized by loss of consciousness and focal neural deficits, which were unusual symptoms in the patient, who was a medical intern with type 1 diabetes and currently being treated with regular and NPH insulin." (PMID 35858952, 2022). "Patients with type 1 diabetes were prescribed one basal insulin, including NPH and glargine plus fast-acting insulin such as regular insulin, aspart, or glulisine, at a daily dose of 0.5 unit/kg." (PMID 32861229, 2022). "In their study, Rivera and colleagues showed that delivery of insulin is possible within 2 h after induction with AP22542, which was sufficient to attenuate the disease symptoms in experimental type-1 diabetes." (PMID 34586617, 2022). "Type 1 diabetes (T1D) is a chronic autoimmune disease characterized by altered glucose sensing and insulin response resulting that may arise from the immune attack of insulin-secreting beta cells in the pancreas." (PMID 36389721, 2022). "The incidence of childhood type 1 diabetes is increasing significantly in European populations, and more MODY patients are becoming obese and insulin resistant as a result of increasing global prevalence of obesity in young adults and children." (PMID 35445424, 2022). "For instance, “Ras signaling”, “metabolic”, “insulin signaling”, “thyroid hormone signaling”, “neurotrophy signaling”, “HIF-1 signaling”, “primary immunodeficiency”, and “type I diabetes mellitus”." (PMID 35317849, 2022). "The introduction of insulin preparations (insulin analogs) has better protective effective outcomes and improved convenience of subjects than NPH insulin in subjects with type-I diabetes." (PMID 35723344, 2022). "Therapy for type 1 diabetes (T1DM) focuses on maintaining optimal blood glucose levels, achieved with intensive insulin treatment, proper nutrition, and physical activity." (PMID 36364951, 2022). "Insulin replacement is an available treatment for autoimmune type 1 diabetes mellitus (T1DM)." (PMID 36551798, 2022). "Adherence to insulin and blood glucose monitoring (BGM) is insufficient in adolescents and young adults (AYAs) with type 1 diabetes (T1D) worldwide and in Qatar." (PMID 38515508, 2022). "Evidence has shown that intensive insulin therapy guided by frequent SMBG delays the onset and slows the progression of microvascular complications in patients with type 1 diabetes." (PMID 36251516, 2022). "For type 1 diabetes (T1DM), evidence of an effect of insulin on cancer incidence is limited and variable." (PMID 35681699, 2022). "Type 1 diabetes (T1D) or insulin-dependent diabetes mellitus (IDDM) is a polygenic disorder possibly triggered by environmental factors that results from a T cell-mediated autoimmune attack against the insulin-producing β-cells localized in the pancreatic islets of Langerhans." (PMID 35155683, 2022). "Firstly, we investigated if resistance training would be able to preserve insulin secretion in beta cells exposed to an in vitro model of type 1 diabetes (T1D), and if such an effect could be mediated by exercise-induced factors released in the bloodstream." (PMID 36012692, 2022). "In type 1 diabetes with insulinopenia, the IGFBP-1 levels are high because of low levels of portal insulin." (PMID 35586622, 2022). "In individuals with type 1 diabetes mellitus (T1DM), the mentioned hormonal balance, especially between insulin and glucagon, is disturbed." (PMID 36339413, 2022). "During the COVID-19 pandemic, HbA1c levels, PRISM scores, insulin infusion times, and PICU stays were higher/longer in the entire research group and in children with newly diagnosed Type 1 diabetes, in Turkey." (PMID 35844756, 2022).